ALDH3B1 (aldehyde dehydrogenase 3 family member B1)
Diseases named in the same sentence as ALDH3B1 in open-access papers:
ALDH3B1 is named in the same sentence as 27 diseases in open-access papers, as found by Europe PMC text mining. Sharing a sentence is not in itself a finding about the gene and the disease. The quoted sentences say what the papers report.
lung carcinoma (9 papers, 2017 to 2023). "This is the first report on the regulatory polymorphism of ALDH3B1, significantly altering lung cancer risk by regulating the detoxification potential of the enzyme." (PMID 36899086, 2023). "Furthermore, we observed a poor response and decreased OS of the lung cancer patients with the variants rs3764821 (ALDH3B1) and rs3748523 (RAD52) for both first- and second-line chemotherapy." (PMID 36899086, 2023). "Unadjusted logistic regression revealed strong association of rs3764821 of ALDH3B1 (G vs. A: OR = 2.64, 95% CI = 1.63–4.29, p = 0.00009***) and rs3748523 of RAD52 (G vs. C: OR = 1.69, 95% CI = 1.17–2.47, p = 0.006**) with lung cancer in additive model." (PMID 36899086, 2023). "Expression pattern and clinical significance studies have found that ALDH3B1 was significantly highly expressed in lung cancer, and can be an independent prognostic factor for lung cancer." (PMID 34249078, 2021). "ALDH3B1 expression was also found to be upregulated in a high percentage of human tumors, particularly in lung cancer." (PMID 31534455, 2019). "Interestingly, rs3764821 of ALDH3B1 and rs3748523 of RAD52 were associated with lung cancer in tobacco and betel quid chewers." (PMID 36899086, 2023). "In a variety of cancers, including lung cancer, breast cancer, and colorectal cancer, the enzyme aldehyde dehydrogenase 3B1 (ALDH3B1), which catalyzes the oxidation of aldehydes to the appropriate carboxylic acids, has been discovered to be important cancer stem cell marker." (PMID 36814901, 2023). "Similarly, ALDH3B1, which is involved in oxidative stress, is highly expressed in lung cancer." (PMID 35852874, 2022). "In silico and qRT-PCR analysis clearly supported the notion that, NRF2 directly binds to the ARE sequences located in the promoter regions of ALDH3B1, NAMPT, and PTGES genes and induces their expression in lung cancer." (PMID 29050246, 2017).
glioma (6 papers, 2021 to 2025). A benign or malignant brain and spinal cord tumor that arises from glial cells (astrocytes, oligodendrocytes, ependymal cells). "After silencing ALDH3B1, glioma cells suffer from G2/M arrest and epithelial-mesenchymal transition (EMT) inhibition." (PMID 37251940, 2023). "Notably, ALDH3B1 is found to be important for glioma cell proliferation." (PMID 38570607, 2024). "Compared with normal glial cells, the expression of ALDH3B1 and CTSZ is significantly upregulated in glioma cells." (PMID 40129966, 2025). "ALDH3B1 and ALDH16A1 are preferentially overexpressed in HGG and can promote the proliferation and migration of glioma cells by regulating cell cycle and EMT processes." (PMID 36694633, 2023). "Based on our scoring system, three out of five ALDHs (ALDH3A1, ALDH3B1 and ALDH16A1) were identified as unfavorable biomarkers for gliomas." (PMID 35116021, 2021). "In the LGG cohort from the TCGA dataset, ALDHs including ALDH2, ALDH6A1, ALDH5A1, ALDH9A1, ALDH1A1 were upregulated in WHO grade II gliomas while the increased expression of ALDH16A1, ALDH3B1, ALDH3A2, ALDH1A2, ALDH3A1 was found in WHO III grade gliomas." (PMID 35116021, 2021). "Importantly, silencing ALDH3B1 and ALDH16A1 expression induced cycle arrest at the G2/M phase and inhibited the epithelial-mesenchymal transition in the glioma cells." (PMID 35116021, 2021). "Critically, ALDH3B1 and ALDH16A1 could also affect the expression of cyclin B1 and aurora A, G2/M cell cycle checkpoints that modulate glioma cells proliferation." (PMID 35116021, 2021). "Accordingly, we focused on the role of ALDH3B1 and ALDH16A1 in gliomas." (PMID 35116021, 2021). "Analysis of the TCGA dataset showed that ALDH16A1, ALDH3B1, ALDH1A3, ALDH3A1, ALDH7A1 were significantly increased in IDH wildtype gliomas, while ALDH2, ALDH6A1, ALDH5A1, ALDH1A1, ALDH1L2, ALDH18A1, ALDH1B1 expression were higher in IDH mutant gliomas than IDH wildtype gliomas." (PMID 35116021, 2021). "Therefore, ALDH3B1 and ALDH16A1 could promote glioma progression by regulating cell proliferation and migration." (PMID 35116021, 2021).
epilepsy (3 papers, 2021 to 2024). A brain disorder characterized by episodes of abnormally increased neuronal discharge resulting in transient episodes of sensory or motor neurological dysfunction, or psychic dysfunction. "The functions of Mvd, Lancl1, Aldh3b1 and Hsdl2 in epilepsy are still worthy to be explored in our future studies." (PMID 36894540, 2023). "ALDH3B1 also protects cells from oxidative stress and may have protective roles in various brain diseases including epilepsy." (PMID 38396970, 2024). "Thus, it is indicated that ALDH3B1 may have a protective role in various brain diseases including epilepsy." (PMID 34555062, 2021). "The results showed that pre-treatment with pyridoxine only had a certain auxiliary effect in epilepsy induced by tutin, suggesting that Aldh3b1 might not be a main target of tutin." (PMID 36894540, 2023).
glioblastoma (2 papers, 2021 to 2023). The most malignant astrocytic tumor (WHO grade IV). "Moreover, ALDH3B1 and ALDH16A1, two main contributors of the scoring system, could affect glioblastoma cell proliferation and migration by inducing cell-cycle arrest and the epithelial-mesenchymal transition." (PMID 35116021, 2021).
lung adenocarcinoma (2 papers, 2022 to 2024). A carcinoma that arises from the lung and is characterized by the presence of malignant glandular epithelial cells. "Studies have validated that the expression of ALDH3B1 is elevated in lung adenocarcinoma tissues compared to normal tissues." (PMID 38256214, 2024). "Studies have confirmed that ALDH3B1 is expressed at higher levels in lung adenocarcinoma tissues than in normal tissues." (PMID 36110123, 2022).
pancreatic cancer (2 papers, 2023 to 2025). "High expression of ALDH1L1, ALDH3A1, and ALDH3B1 was associated with shorter overall survival, while ALDH5A1 expression was associated with longer overall survival of pancreatic cancer patients." (PMID 40868269, 2025). "ALDH3A1 and ALDH3B1 were found to be upregulated and ALDH1L1 downregulated in pancreatic cancer versus normal tissues." (PMID 40868269, 2025). "In this study comprehensively analyzed ALDHs in PAAD and identified four genes (ALDH1L1, ALDH3A1, ALDH3B1, ALDH5A1) as prognostic indicators for pancreatic cancer." (PMID 40868269, 2025). "Based on survival analysis, 6 out of 32 MMRGs (LDHA, ALDH3B1, LDHAL6B, PKM, ALDH3A1, and PGAM4) in pancreatic cancer were of survival significance." (PMID 36814901, 2023). "ALDH1L1, ALDH3A1, ALDH3B1, and ALDH5A1 may serve as potential prognostic markers and predictors of chemotherapy response in pancreatic cancer patients." (PMID 40868269, 2025).
cholangiocarcinoma (1 paper, 2021). A carcinoma that arises from the intrahepatic biliary tree (intrahepatic cholangiocarcinoma) or from the junction, or adjacent to the junction, of the right and left hepatic ducts (hilar cholangiocarcinoma). "The results showed that ALDH3B1 and ALDH3B2 were highly expressed in hilar cholangiocarcinoma, which indicated the important role of ALDH3 family in the development of cholangiocarcinoma." (PMID 34907179, 2021).
chronic pancreatitis (1 paper, 2023). A chronic inflammatory process causing damage and fibrosis of the pancreatic parenchyma. "ALDH3B1, ENO1, ALDH2, GAPDH, and LDHC had significant differences among grades, while ALDH3B1, PKM, and ALDH3B2 differed among chronic pancreatitis histories." (PMID 36814901, 2023).
colon cancer (1 paper, 2020). "This speculation is supported by several pieces of evidence, demonstrating a specific elevated expression of ALDH1B1 in colon cancer; ALDH3B1 in lung, breast, ovarian, and colon cancer; ALDH3A1 in lung cancer; and ALDH7A1 in prostate cancer." (PMID 35582039, 2020).
diabetes (1 paper, 2017). "The ALDH3B1 gene had its function related to oxidation of lipid-derived aldehydes generated in the human plasma membrane and is associated to diabetes in humans." (PMID 28118362, 2017).
endometrial cancer (1 paper, 2024). Primary or metastatic malignant neoplasm involving the endometrium (mucous membrane that lines the endometrial cavity). "The proteomic profiling of endometrial cancer cell lines revealed that ECC-1 and RL95-2 shared the ALDH isoforms ALDH3A1, ALDH3A2, ALDH3B1, ALDH3B2, ALDH7A1, ALDH9A1, and ALDH18A1 in their proteome." (PMID 38893151, 2024).
gout (1 paper, 2024). A condition characterized by painful swelling of the joints, which is caused by deposition of urate crystals. "Combining the results of the three-step SMR analysis, we found that genetically predicted elevated levels of CpG site cg25402137 located in ALDH3B1, reduced the risk of gout by down-regulating ALDH3B1 expression levels." (PMID 39734218, 2024). "Ultimately, eight genes were identified as possible drug targets in gout, including three risk genes (ALDH3B1, NRBP1, SUMF1) and three protective genes (FCGR2B, RCE1, SLC7A7)." (PMID 39734218, 2024). "At the methylation level, genetically predicted methylation of cg25402137 reduces the risk of gout development by down-regulating the expression level of ALDH3B1." (PMID 39734218, 2024). "Evidence from the SMR analysis (P < 0.05) further strengthened the reliability of the 8 potential therapeutic targets for gout also revealed that high levels of ALDH3B1 reduced the gout risk possibly modified by the methylation site cg25402137." (PMID 39734218, 2024). "At the methylation sites in eight gene regions, we only found that genetically predicted each SD increase in methylation of cg25402137 at the ALDH3B1 was associated with a reduced risk of gout (β = -0." (PMID 39734218, 2024). "SMR analysis of DNA methylation levels and gout causal gene expression identified seven DNA methylation sites (ALDH3B1: cg18412889, cg23121335, cg25402137; IL2RB: cg25246692, cg11558856; NRBP1: cg15478930; SUMF1: (cg24840601) modifications may regulate ALDH3B1, IL2RB, NRBP1 and SUMF1 expression." (PMID 39734218, 2024). "Eight potential therapeutic targets (ALDH3B1, FCGR2B, IL2RB, NRBP1, RCE1, SLC7A7, SUMF1, THBS3) for gout were identified in the discovery cohort using MR analysis." (PMID 39734218, 2024).
Obesity (1 paper, 2025). Accumulation of substantial excess body fat. "We found significantly higher (by 1.7-fold) expression of ALDH3B1 mRNA in the liver of individuals with obesity/overweight, and a significant correlation between ALDH3B1 expression and BMI." (PMID 40359692, 2025). "Therefore, the oxidative stress related to obesity may be a reason for the observed up-regulation of ALDH3B1 in the liver." (PMID 40359692, 2025).
ovarian tumors (1 paper, 2023). "Conversely, in another study, they showed that ALDH3B1 had an immunoreactivity of 89% in ovarian tumors, such as serous papillary adenocarcinomas, clear cell adenocarcinomas, endometroid adenocarcinomas, and mucinous adenocarcinomas." (PMID 37686694, 2023). "Unlike ALDH3A1 and ALDH3B1, there is evidence that ALDH1A3, ALDH3A2, and ALDH7A1 are overexpressed in ovarian tumors compared to normal ovarian tissues." (PMID 37686694, 2023).
pancreatic adenocarcinoma (1 paper, 2025). "Next, the expression of ALDH1L1, ALDH3A1, ALDH3B1, and ALDH5A1 in pancreatic adenocarcinoma (PAAD) samples was compared with that of matching TCGA and GTEx normal samples using GEPIA2." (PMID 40868269, 2025).
perihilar cholangiocarcinoma (1 paper, 2021). "We analyzed the expression of ALDHs in 8 paired tumor and peritumor perihilar cholangiocarcinoma (pCCA) tissues and found that ALDH3B1 and ALDH3B2 were upregulated in tumor tissues." (PMID 34907179, 2021).
cancer (16 papers, 2008 to 2025). A tumor composed of atypical neoplastic, often pleomorphic cells that invade other tissues. "The results of methylation analysis further expanded our understanding of CEDGs expression, explaining the decreased expression of some CEDG in a certain cancer type, like ALDH3B1 in LUSC and MRGPRF in UCEC." (PMID 40478912, 2025). "Aldehyde dehydrogenase 3 family member B1 (ALDH3B1) is overexpressed in many human cancer types; increased expression of ALDH3B1 was also observed in MCF-7SCs." (PMID 35631492, 2022). "Upregulation of ALDH3B1 in BRAF(+) PTCs may constitute a mechanism of cancer cell survival." (PMID 26625260, 2015). "Most of CEDGs like CCND1, ALDH3B1, MYEOV were frequently hypomethylated in cancer, while FGF3, FGF4, MRGPRF and CPT1A were hypermethylated in most cancers." (PMID 40478912, 2025). "LDHA, ALDH3B1, and ALDH3A1 are all connected to the genesis and development of various cancers and play a role in mitochondrial energy metabolism." (PMID 36814901, 2023). "According to the classification of normal tissues and tumor tissues, it was found that the expression of ALDH3B1, ALDH18A1, etc., increased in a variety of cancers, but ALDH9A1 and ALDH2 showed the opposite trend in UCEC." (PMID 34670872, 2021). "Scant literature exists to link ALDH3B1, ALDH7A1, and ALDH18A1 to cancer, although, these studies provide initial evidence that these isoforms favor tumorigenesis." (PMID 31974410, 2020). "It is noteworthy that some isoforms, such as ALDH2, ALDH3A2, ALDH3B1, and ALDH5A1, are expressed at similar levels across cancer types." (PMID 30220009, 2019). "ALDH1A2 is expressed at very low level in all types of cancer, whereas ALDH1B1, ALDH3B1, and ALDH5A1 are expressed at medium level universally, implying a ubiquitous role of these isoforms." (PMID 30220009, 2019). "Aldehyde dehydrogenase (ALDH1B1, ALDH2, ALDH3B1, ALDH3B2, ALDH7A1 and ALDH9A1) were involved in the resistance against cyclophosphamide/carboplatin in cancer chemotherapy." (PMID 28225065, 2017). "However, no cancer-type specific expression preference of ALDH1A2, ALDH1B1, ALDH3B1, and ALDH5A1 has been observed." (PMID 30220009, 2019).
tumor (14 papers, 2018 to 2025). "It is further shown that ALDH3A1 and ALDH3B1 are overexpressed in tumor tissues and predict poorer patient outcomes." (PMID 40868269, 2025). "Consistently, Tumor Mutational Burden (TMB) analysis showed KRAS mutations were higher in tumors with high ALDH3A1 and ALDH3B1 expression (76% and 81%, respectively) than in those with low expression (44% and 38%, respectively)." (PMID 40868269, 2025). "The results showed that ALDOA, ADH1B, and ALDH3B1 were significantly overexpressed in tumor samples compared to normal samples." (PMID 38256214, 2024). "At the single-cell level, tumor cells expressed low levels of CHST11 compared with ALDH3B1, EGFR, ERAP2, MSLN, and NCEH1." (PMID 37251940, 2023). "Except for ALDH3B1 and NCEH1, the other three genes have been reported to be associated with tumor progression and gemcitabine resistance in PC." (PMID 37251940, 2023). "Three out of the five components of our risk score, ALDH3A1, ALDH3B1 and ALDH16A1, were identified as tumor promoters." (PMID 35116021, 2021). "In this study, the expression pattern of 19 ALDH family members in 8 paired pCCA tumor and peritumor tissues were first analyzed with mRNA sequencing and ALDH3B1 and ALDH3B2 was found upregulated in pCCA tissues." (PMID 34907179, 2021). "Select genes including ALDH3B1, CEACAM5, IL8, PYGO2, and WWTR1, exhibited pronounced activity in promoting tumor formation and establishing gene dependencies critical for tumorigenicity." (PMID 38851782, 2024). "The expression of ALDH3B1 and ALDH3B2 was then verified with qPCR in paired tumor and peritumor iCCA, pCCA, and dCCA tissues (n = 6)." (PMID 34907179, 2021). "Among these differentially expressed ALDHs, ALDH3B1 and ALDH3B2 were highly expressed in tumor tissues compared with the peritumor tissues with the largest fold of changes." (PMID 34907179, 2021). "Except for ALDH3B1, which was statistically significant, the expression of the other 5 ALDH family members decreased in tumor tissues." (PMID 34670872, 2021). "Some tumor type-specific DEs were observed for ALDH1L1, ALDH3B1, ALDH3B2, ALDH4A1 and ALDH7A1." (PMID 29426835, 2018). "Moreover, our in vitro experiments substantiated that ALDH3B1 and ALDH16A1 could affect tumor cells proliferation and epithelial-mesenchymal transition." (PMID 35116021, 2021). "ALDH3B1 and ALDH16A1 could influence tumor cell proliferation and migration." (PMID 35116021, 2021).
digestive system disease (1 paper, 2024). "Briefly, for instance, targeting ALDH3B1 may be beneficial for 1 digestive system disease (Inflammatory conditions of jaw)." (PMID 39734218, 2024).
ALDH3B1 also shares sentences with these, for which no sentence is quoted: brain diseases (2 papers); breast carcinoma (1); chronic myeloid leukaemia (1); colorectal cancer (1); neuroblastoma (1); prostate carcinoma (1); pyridoxine-dependent epilepsy (1); thyroid cancer (1).